MDK (midkine)
Diseases named in the same sentence as MDK in open-access papers (continued):
Sharing a sentence is not in itself a finding about the gene and the disease.
ovarian carcinoma (continued). "Importantly, CA125 and HE4 are present in this quadrant, as well as other proteins that have been reported to be elevated in the sera of women with ovarian cancer, such as interleukin-6, midkine, folate receptor-alpha, KLK6, and hK11." (PMID 29051715, 2017). "Thus, MDK targeted therapy should suggest an effective treatment for ovarian cancer." (PMID 35935940, 2022). "Thus, MDK may participate in two-way communication between CAFs and ovarian cancer cells and act in an autocrine or paracrine manner." (PMID 36352420, 2022). "The purpose of this study was to characterise changes in the plasma concentrations of MDK in association with ovarian cancer and compare its diagnostic performance (as assessed by the AUC) with that of AGR2 (a recently reported circulating biomarker of ovarian cancer) and CA125 in symptomatic women." (PMID 20525245, 2010). "Its downstream targets include anti-apoptotic proteins such as Bcl-2, and MDK also facilitates drug efflux by upregulating ABC transporters, such as MDR1 and ABCG2, leading to multidrug resistance in gastric, leukemia, and ovarian cancer models." (PMID 40500394, 2025). "The median plasma concentrations of both ir MDK and ir AGR2 were significantly greater in women with ovarian cancer (909 pg/ml and 765 pg/ml, respectively n = 46) than in normal healthy women (383 pg/ml and188 pg/ml, respectively n = 61) (p < 0.001)." (PMID 20525245, 2010). "The data obtained confirm the utility of both MDK and AGR2 as plasma biomarkers for ovarian cancer and, when combined in a multi-analyte panel, significantly improve the diagnostic efficiency of CA125." (PMID 20525245, 2010). "The data obtained in this study confirm that both MDK and AGR2 individually display utility as biomarkers for ovarian cancer and that in a multi-analyte panel significantly improve the diagnostic utility of CA125 in symptomatic women." (PMID 20525245, 2010). "It is of note, however, that plasma concentrations of MDK and AGR2 display differential responsiveness in women with ovarian cancer when compared to CA125." (PMID 20525245, 2010). "Interestingly, a heparin-binding growth factor, midkine (MK), derived from CAFs, provides cisplatin resistance to oral squamous cell carcinoma (OSCC), lung cancer, and ovarian cancer cells by enhancing the expression levels of the lncRNA-ANRIL." (PMID 37065872, 2023). "To assess whether targeting MDK would augment the anti-tumor activity of IFN-γ in ovarian cancer, we treated the SKOV3 cells with a potent MDK inhibitor, iMDK, and then evaluated the effect of MDK inhibition on the tumoricidal activity of IFN-γ." (PMID 36672515, 2022). "In addition, 5 genes such as ARMCX2, COL1A1, midkine (MDK), MEST and MLH1) were methylated in drug-resistant ovarian cancer cells." (PMID 34631583, 2021). "Taken as a whole, these data suggest that while MDK may not be sufficient as a solo biomarker, it has abundant potential as a component of ovarian cancer biomarker panels." (PMID 40429950, 2025). "MDK is significantly elevated in ovarian cancer relative to normal tissues, and MDK levels could detect ovarian cancer samples from normal tissues and benign tumors." (PMID 40429950, 2025). "The data obtained in this study confirm that the measurement of plasma concentrations of MDK and AGR2 individually display utility as biomarkers for ovarian cancer and that when included in a multi-analyte panel may significantly improve the diagnostic utility of CA125 in symptomatic women." (PMID 20525245, 2010).
neuroblastoma (16 papers, 2008 to 2025). Neuroblastoma (NB) is the most common solid, extracranial childhood tumor. "Moreover, elevated MDK blood levels can be linked to poor prognostic factors in neuroblastoma patients, supporting the relevance of MDK in neuroblastoma tumorigenesis." (PMID 38098484, 2023). "In addition, increased midkine expression is associated with poor prognosis in oral squamous cell carcinoma, neuroblastoma, and bladder carcinoma." (PMID 24083030, 2013). "ScRNA-seq revealed 13 immunosuppressive interactions in the TME of neuroblastoma, two effectors of which, Midkine (MDK) and Macrophage Migration Inhibitory Factor (MIF), were validated as candidate targets across multiple published datasets." (PMID 39908652, 2025). "To validate the potential roles of MIF and MDK in neuroblastoma, we confirmed their protein expression by mass-spectrometry of 11 neuroblastoma tumoroids." (PMID 39908652, 2025). "Further research using more complex models with additional immune cell types is needed to clarify the role of MDK in the neuroblastoma TME and its potential as a target for enhancing immunotherapy." (PMID 39908652, 2025). "To study this interaction, we generated neuroblastoma cell lines with genetic depletion of MDK (SK-N-AS-shMDK and SH-SY5Y-shMDK) or MIF (SK-N-BE2C-shMIF and Kelly-shMIF) using shRNA-mediated silencing." (PMID 39908652, 2025). "Taken together, these data indicate potential immunosuppressive roles of MIF and MDK in the neuroblastoma TME." (PMID 39908652, 2025). "While in neuroblastomas PTN expression is linked to good prognosis, high MDK mRNA levels are detected in tumors with poor prognosis." (PMID 38098484, 2023). "In vitro and in vivo studies with tumor xenografts depict a suppressed growth of neuroblastoma cells upon intratumoral administration of RNA aptamers specific for MDK." (PMID 38098484, 2023). "In vitro studies using primary neuroblastomas and neuroblastoma cell lines suggest that MDK not only promotes peripheral neoplasms but is also involved in tumor growth and differentiation in the CNS." (PMID 38098484, 2023). "MDK-Notch 2 signaling has also been shown to promote neuroblastoma through the downstream effector Hes-1." (PMID 37240085, 2023). "Doxorubicin-resistant (SK-N-SH/DoxR) neuroblastoma cells SK-N-SH were found to protect the neighboring drug-sensitive cells against doxorubicin via the secretory cytokine MDK." (PMID 37240085, 2023). "In a neuroblastoma and osteosarcoma cells study, MDK induced cytoprotective function in the neighboring drug-sensitive cells against cell death induced by doxorubicin via the Akt pathway." (PMID 37240085, 2023). "MDK is an important factor in the development and progression of high-grade astrocytoma and neuroblastoma suggesting a role as tumor promoter in the brain." (PMID 34502484, 2021). "Midkine protein expression was reported to be correlated with poor prognosis in patients with neuroblastomas, astrocytomas, pancreatic head carcinomas, or gastrointestinal stromal tumours." (PMID 18682710, 2008). "•Multi-omics identified MIF and MDK as immunosuppressive targets in neuroblastoma." (PMID 39908652, 2025). "We therefore specifically quantified MIF and MDK secretion by neuroblastoma tumoroids." (PMID 39908652, 2025). "Compared to healthy tissues, both MIF and MDK were overexpressed in neuroblastoma." (PMID 39908652, 2025). "Analysis of both primary neuroblastoma tissues and cell lines reveals high expression of MDK mRNA." (PMID 37240085, 2023). "However, recently it was described that macrophage migration inhibitory factor (MIF) and midkine (MDK) are expressed in neuroblastoma, factors that are known to be involved in metastasis in other cancers." (PMID 38087370, 2023). "Moreover, RNA aptamers against MDK hold great potential for therapeutic treatment of neuroblastomas." (PMID 38098484, 2023). "Unraveling the involvement of MIF and MDK in neuroblastoma metastasis could provide important information in the future." (PMID 38087370, 2023).
neuroblastoma (continued). "Overexpression of MDK in neuroblastoma posed drug resistance towards doxorubicin and etoposide." (PMID 37240085, 2023). "This hypothesis has been supported by reduced tumor growth in several MDK-depleted neuroblastoma cell lines." (PMID 38098484, 2023). "MDK is found to provide cytoprotective function in neuroblastoma." (PMID 37240085, 2023). "For example, MDK-Notch signaling, Notch2 as a functional receptor of MDK, regulates the epithelial-mesenchymal transition and chemotherapy resistance in pancreatic cancer and promotes the development of neuroblastoma." (PMID 34977035, 2021). "MDK has been found to be over-expressed in various human cancers, including esophageal, gastric, colon, pancreatic, hepatocellular, lung, breast, and urinary bladder carcinomas, as well as neuroblastomas and Wilms' tumors." (PMID 18275606, 2008). "In addition, high MIF and MDK expression was significantly associated with inferior event-free and overall survival of neuroblastoma patients, which was independent of MYCN amplification." (PMID 39908652, 2025). "To investigate the roles of MIF and MDK on CAR T-cell modulation, we used CAR T-cells targeting GPC2, which have shown robust safety and efficacy in diverse preclinical models of neuroblastoma and are currently being tested clinically (NCT05650749)." (PMID 39908652, 2025). "Since CAR T-cell therapy is a promising upcoming treatment strategy for neuroblastoma, we investigated the suppressive effect of MIF and MDK on T cells specifically." (PMID 39908652, 2025). "In primary neuroblastoma tumours, two neurotrophic factors, pleiotrophin (PTN) and midkine (MDK), are highly expressed and have been postulated to bind and activate ALK in vitro." (PMID 34769149, 2021). "Intriguing studies, employing the neuroblastoma SH-SY5Y and IMR-32 cell lines, demonstrated that MDK and ALK are ethanol-responsive and that the activation of ALK signaling by ethanol is dependent on MDK expression." (PMID 28553209, 2017). "Midkine levels were significantly higher (p < 0.0001) in neuroblastoma patients compared to non-tumor controls." (PMID 37240085, 2023). "Therefore, it is not surprising that MDK has been found to be over-expressed in various human cancers, including esophageal, gastric, colon, pancreatic, hepatocellular, lung, breast, and urinary bladder carcinomas, neuroblastomas, and Wilms' tumors." (PMID 18275606, 2008).
pancreatic cancer (14 papers, 2008 to 2025). "In tissue microarray analysis of histological subtypes of pancreatic cancer, moderate to strong MDK expression was found in 36% (20 of 56) and 38% (21 of 56) of ductal adenocarcinomas, respectively." (PMID 37240085, 2023). "In vitro studies suggest that MDK promotes proliferation and migration of pancreatic cancer cells and is furthermore contributing to chemoresistance in ductal adenocarcinomas." (PMID 38098484, 2023). "Another novel therapeutic strategy for peripheral tumors expressing MDK is the promotor-based conditionally replicative adenovirus therapy, which has been tested in pancreatic cancer cell lines in vitro." (PMID 38098484, 2023). "MDK is upregulated in the majority of cancers (at least 20 different cancer types), such as breast, lung, ovary, prostate, colon, gastric and pancreatic cancers, whereas its expression is generally low or undetectable in normal adult tissues." (PMID 35747815, 2022). "An important example, MDK is overexpressed in about 50% of pancreatic cancer patients, and participates in the tumor cells chemotherapy resistance through the Notch 2 signaling pathway." (PMID 29872508, 2018). "We examined midkine mRNA expression and midkine protein expression by seven human pancreatic cancer cell lines (AsPC-1, BxPC-3, CFPAC-1, HPAC, MIAPaCa-2, PANC-1, and Suit-2), as well as by non-cancerous pancreatic tissue and pancreatic cancers." (PMID 18717994, 2008). "Ad5MK has an anti-tumor effect against human pancreatic cancer cell lines that express midkine mRNA." (PMID 18717994, 2008). "We examined the expression of midkine mRNA in seven human pancreatic cancer cell lines by TaqMan PCR." (PMID 18717994, 2008). "The present study aimed to ascertain whether suppression of midkine (MK) expression in pancreatic cancer cells inhibits metastasis to the liver." (PMID 24179520, 2013). "Midkine expression was increased in pancreatic cancer cell lines and pancreatic cancer tissues." (PMID 18717994, 2008). "Expression of midkine mRNA in human pancreatic cancer cells." (PMID 18717994, 2008). "Therefore, to determine the specificity of Ad5MK replication, we used pancreatic cancer cell lines with different levels of midkine expression and then examined E1A expression by Western blotting." (PMID 18717994, 2008). "Our single-cell ligand-receptor bubble plot analysis showed that in pancreatic cancer epithelial cells, the expression levels of MIF, MDK, and LGALS9 were significantly higher when NAT10 and KRT8 were highly expressed than when they were low-expressed." (PMID 41203621, 2025). "In pancreatic cancer cells, there was an increase in proliferation when MDK-depleted cells were exposed to MDK compared to the MDK-depleted cells without the treatment." (PMID 37240085, 2023). "Midkine (MDK) is a heparin-binding growth factor that is highly expressed in many malignant tumors, including lung, esophageal, stomach, colon, hepatocellular, breast, renal and pancreatic carcinoma." (PMID 23976985, 2013). "We assessed the expression of midkine mRNA in 22 pancreatic cancer samples and 18 adjacent non-cancerous pancreatic tissue samples by TaqMan PCR." (PMID 18717994, 2008). "Expression of midkine mRNA was significantly stronger in pancreatic cancers than in non-cancerous pancreatic tissues." (PMID 18717994, 2008). "Expression of midkine mRNA was significantly stronger in pancreatic cancer than in non-cancerous tissue (p < 0.001)." (PMID 18717994, 2008). "The midkine mRNA/β-actin mRNA ratio of pancreatic cancer and non-cancerous pancreatic tissue was 0.60 ± 0.55 and 0.22 ± 0.13, respectively." (PMID 18717994, 2008). "We showed that most human pancreatic cancer cell lines (6 out of 7 lines tested) express midkine to some extent and that the level of midkine mRNA expression in pancreatic cancer tissues is significantly higher than in non-cancerous pancreatic tissues." (PMID 18717994, 2008).
pancreatic cancer (continued). "In conclusion, MDK has emerged as a pivotal driver of PCAND pathogenesis and may function as a blood-based biomarker for discriminating between PCAND and T2DM in populations with new-onset diabetes, thereby facilitating the advancement of early detection strategies for pancreatic cancer." (PMID 40709672, 2025).
prostate carcinoma (14 papers, 2008 to 2025). A carcinoma that arises from epithelial cells of the prostate gland. "A search of the literature revealed that CD44 was required for SRGN to promote aggressiveness of non-small cell lung cancer 41, and that CD44-positive prostate cancer cells were significantly more susceptible to the inhibitory effect of MDK-knockdown on cell viability." (PMID 33456569, 2021). "It was also reported that knocking down endogenous MDK expression by siRNA enhanced TNF-α-induced apoptosis through activation of caspase-3 in prostatic cancer cells, and MDK had a protective role against cardiac ischemic/reperfusion injury." (PMID 40943439, 2025). "Then, we manipulated the expression of MDK through plasmid transfection in prostate cancer cell lines that were stably knocking down of GPC2, and further measured the protein levels of PI3K, p-PI3K, AKT, as well as p-AKT." (PMID 39014225, 2024). "Further experiments confirmed that GPC2 positively regulated PI3K/AKT signaling though MDK, and overexpression of MDK attenuated the inhibitory effect of GPC2 knockdown on malignant behaviors of prostate cancer." (PMID 39014225, 2024). "GPC2 promoted prostate cancer cell proliferation, migration, and invasion via MDK-mediated activation of PI3K/AKT signaling pathway." (PMID 39014225, 2024). "GPC2 promotes prostate cancer cell proliferation, migration, and invasion via MDK-mediated activation of PI3K/AKT signaling pathway." (PMID 39014225, 2024). "Immunohistochemistry of prostate cancer patient samples revealed that of the 80 clinical cancers examined, 69 specimens (86.3%) were immunoreactive for MDK, with metastatic lesions showing higher expression than the corresponding primary tumors." (PMID 37240085, 2023). "Midkine has been studied in prostate cancer with neuroendocrine differentiation and elevated blood levels of Midkine has been suggested as a biomarker in SI-NET." (PMID 36959559, 2023). "A study has also shown that silencing of MDK along with quercetin treatment can be a good approach to target prostate cancer stem cells (CSCs)." (PMID 37240085, 2023). "In a further xenograft model related to prostate cancer, siRNA/atelocollagen was used to silence the growth factor midkine (MK)." (PMID 24276320, 2013). "Normal and prostate cancer tissue microarray slides were immunohistochemically stained for midkine, using rabbit anti-midkine antibodies and ABC elite kit with DAB substrate, and counterstained by hematoxylin." (PMID 18275606, 2008). "In this study, we found that fetal bovine serum stimulated MDK expression in a prostate cancer cell line LNCaP." (PMID 18275606, 2008). "Given the anti-apoptotic role of MDK in prostate cancer cells, our findings further support the new strategy to target MDK using specific siRNA as shown by a recent study." (PMID 18275606, 2008). "To simplify, our research reveals that GPC2 promotes prostate cancer progression via MDK-mediated activation of PI3K/AKT signaling pathway, and GPC2 might be a potential therapeutic target in prostate cancer." (PMID 39014225, 2024). "To explore whether GPC2 promotes the activation of PI3K/AKT signaling via MDK in prostate cancer, we first confirmed the physical interaction between GPC2 and MDK through immunoprecipitation assay." (PMID 39014225, 2024). "Take together, our results indicated that overexpression of MDK could reverse the inhibitory effect of GPC2 knockdown on malignancy of prostate cancer." (PMID 39014225, 2024). "Small interfering RNA (siRNA) targeting MDK could almost completely inhibit the MDK secretion in prostate cancer cells and enhance the cytotoxicity of paclitaxel-mediated chemotherapy." (PMID 37240085, 2023). "In prostate cancer, MDK was found to be induced by TNF-α via the NFκB pathway." (PMID 37240085, 2023). "MDK is considered one of the most reliable prognostics for short prostate cancer-specific survival." (PMID 34209090, 2021).